CCL5 (C-C motif chemokine ligand 5)
Diseases named in the same sentence as CCL5 in open-access papers (continued):
Sharing a sentence is not in itself a finding about the gene and the disease.
tumor (continued). "In a protein array, lysates of Ptgs1/Ptgs2−/− BRAFV600E early (day 4) tumors displayed 45-fold more CCL5 than COX-sufficient control tumor lysates and a minor (<2-fold) increase in CCL27A." (PMID 29429633, 2018). "For example, CCL5/RANTES and CCL2 are known to recruit immune cell populations like Tregs and TAMs, among others, and have been implicated in tumor aggressiveness and increased metastatic potential." (PMID 30613350, 2018). "To visualize the location of CD11bhiF4/80low TAMs and CD8+ T cells in the tumor site, we used immunofluorescence technique to detect the location of those cells in the tumor tissues of CCL5+/+ mice and CCL5−/− mice." (PMID 29991744, 2018). "To determine the effect of CCL5-deficiency on anti-PD-1 Ab resistance in CRC, we intraperitoneally injected 200 μg anti-PD-1 Ab into CCL5+/+ and CCL5−/− mice every 3–4 days from day 3 to day 16 after tumor challenge." (PMID 29991744, 2018). "The increase in the number of tumor-infiltrating NK cell in Salmonella-treated group is consistent with the increment in Ccl2, Ccl3, and Ccl5 gene expression observed in these groups, since one function of these chemokines is the recruitment of NK cells." (PMID 29410666, 2018). "We found that Sipa1−/− memory CD8+ T cells in tumor tissue further produce Ccl5 (Rantes), which shows potent TCR costimulatory activity for CD4+ T cells in addition to T-cell chemotactic activity." (PMID 29500416, 2018). "There is evidence suggesting possible clinical applications of drugs that are capable of inhibiting the CCR5/CCL5 axis or decreasing CCL5 production/secretion by tumor cells or by the TME." (PMID 29772686, 2018). "CCL5, although it is well known for its pro-tumorigenic role, has recently been promoted as a natural adjuvant for enhancing anti-tumor immune responses." (PMID 29330447, 2018). "For example, CCL2 (MCP‐1) and CCL5 (RANTES) are major attractants of monocyte precursor cells in tumours and, when accumulated, these cells play an important part in tumour non‐responsiveness by suppressing antigen‐specific T cell responses." (PMID 30117676, 2018). "Monocytes from the peripheral blood are recruited in the TME and differentiate into TAMs in response to chemokines, including CCL5, and growth factors produced by stromal and tumor cells." (PMID 29772686, 2018). "Chemokines (CCL2, CCR2, CCL5, etc.)produced by different tumors can actively recruit MDSCs to primary and metastatic tumor sites to inhibit immune cell function within the TME." (PMID 29735917, 2018). "We have previously presented evidence of the important roles of interleukin-6 (IL-6) and chemokine (C-C motif) ligand 5 (CCL5) in TNBC tumor growth and metastasis." (PMID 29898755, 2018). "This group argues that the effect of TBK1/IKKε is at the level of T cells, where IL-2 and IFNγ are increased with inhibition, and at the tumor cell level where TBK1/IKKε inhibition leads to decreased C-C motif chemokine ligand 5 (CCL5) and IL-6." (PMID 30223576, 2018). "To figure out the reasons on the accumulation of CD8+ T cells in the tumor site in CCL5−/− mice, we first detected the percentage of CD8+ T cells in circulating blood in CCL5+/+ and CCL5−/− mice after 3 weeks of tumor challenge." (PMID 29991744, 2018). "In this study, we chose to knockdown both tumor-derived and host-derived CCL5 to decrease the amount of CCL5 as much as possible in mouse models." (PMID 29991744, 2018). "High levels of CCL5 and CD68 are associated with tumor size, degree of tumor invasion, lymphatic metastasis, pathological grading, and tumor thrombus, but are unrelated to patient age and gender." (PMID 29772686, 2018). "The infiltration of NK cells was completely abrogated when CCL5 was silenced in Beclin1-defective tumor." (PMID 29922284, 2018). "Depletion of CD8+ T cells dramatically enhances the tumor growth and liver metastasis in CCL5−/− mice, compared to the isotype Ab treatment group, and their antitumor activity of CCL5-deficiency in CRC was lost." (PMID 29991744, 2018).
tumor (continued). "To figure out which subset of CD8+ T cells was affected by CCL5-deficiency, we analyzed the composition of subpopulation of CD8+ T cells infiltrating into tumor area by FC." (PMID 29991744, 2018). "This suggests that CCL5 regulates the biological behavior of tumor cells through different mechanisms in different cell types." (PMID 29872080, 2018). "Our results suggest that, even in the absence of immune cells, the expression of CCR5 on tumor cells enables tumor growth in an environment where CCL5 is produced, mediated by upreguation of metabolic events." (PMID 29216863, 2017). "Of note, expression of CCL5 was significantly higher in tumours of artLCMV-OVA-treated animals than in those receiving rLCMV-OVA or rAd-OVA (similar trend for Cxcl9)." (PMID 28548102, 2017). "While CCL5 has a role in promoting anti-tumour responses, there is accumulating evidence for CCL5 supporting cancer metastasis and progression." (PMID 29216863, 2017). "If the tumor-promoting effects of hMSCs are largely due to the CCL5/β-catenin pathway, the effects observed with TCM treatment should be reversed by Wnt/β-catenin suppression." (PMID 28542126, 2017). "Together, these findings suggest that MSCs in tumor inflammatory microenvironment are elicited of CCL5, which activate AKT/NF-κB signaling and lead to metastatic growth of CCA cells." (PMID 29088737, 2017). "For example, tumor secrete ligands CCL5, CCL7, and CXCL8, bind to their receptors CCR1 or CXCR2 expressed on subtypes of MDSCs, and attract MDSCs in the tumor microenvironment." (PMID 29299180, 2017). "CCL5 was found to reduce anti-tumor immune response by increasing the presence of tumor-associated macrophages and Treg." (PMID 29371976, 2017). "In this report, an oncolytic Ad (Ad5Δ24) was armed with chemokine genes CCL5 and IL-15 and applied as a recruiter (via CCL5) and sustainer (via IL-15) of CAR-T cells (reactive against the tumor-associated ganglioside GD2) into/within the TME." (PMID 28555136, 2017). "Stromal cells, along with mesenchymal stem cells, are the major sources of chemokines, including CCL5, in the tumor microenvironment." (PMID 29216863, 2017). "Another HCMV gene implicated in tumor development is US28, which encodes a functional chemokine receptor that binds several human chemokines, including CCL2/MCP-1, CCL5/Rantes, and CX3CL1/Fractalkine." (PMID 28228690, 2017). "Collectively the reduced levels of CXCL-1 and CCL5 argue that the direct and indirect stimulation of tumor cell growth by immunological factors and the immune system is reduced in tumors previously exposed to [curcumin + sildenafil]." (PMID 29245915, 2017). "CCL5 has been reported to provide antitumor adjuvanticity or, conversely, to promote carcinogenesis, depending on the tumor environment." (PMID 29375583, 2017). "Expression of CCL5 (RANTES) from an OV has been shown to recruit DC, macrophages, NK, and CD8+ T cells into tumor sites, in association with the development of enhanced tumor antigen-specific CD8+ T cell and NK cell-mediated immune responses." (PMID 28555136, 2017). "The results showed that several genes were highly expressed in tumor, including Cxcl2, Ccl2, Ccl3, Ccl4, and Ccl5." (PMID 28432279, 2017). "The immunohistochemical analysis showed that CCR5 was expressed in 20 of 28 tumor sections analyzed, and CCL5 expression was detected in 22 of 28 tumors." (PMID 29299159, 2017). "Here we demonstrated that the chemokines produced by TAMs, e.g., CCL5, favored tumor invasion and glycolysis." (PMID 29299159, 2017). "Consistent with this, our study reveals a new dimension between ANXA1 and CCL5 to modulate macrophage polarization and tumour cell proliferation." (PMID 29263330, 2017). "CCL5 has been implicated in the recruitment of CD4 + CD25 + Foxp3+ Tregs, leading to the generation of a suppressive environment that supports tumor tolerance." (PMID 29216863, 2017).
tumor (continued). "In this study, we show that TNF-α preactivated-hMSCs exert a much stronger tumor-promoting effect than inactivated hMSCs via CCL5/β-catenin/Slug pathway in CRC development." (PMID 28542126, 2017). "Lastly, while Ccl5 silencing results in ~20% reduction in cell growth in vitro, there was a ~70% reduction in tumor cell growth following Ccl5 KD in vivo." (PMID 28380429, 2017). "It was proven that MSCs within the tumor stroma enhance the metastatic ability of cancer cells, which is dependent on CCL5 signaling via its chemokine receptor CCR5." (PMID 29197379, 2017). "CXCL9 and CCL5 can directly promote tumor growth but the cytokines are also a chemo-attractant which promotes T cell and monocyte infiltration into the tumor microenvironment and the development of T memory cells." (PMID 29137331, 2017). "CCR5 is important for the recruitment of immune cells to the tumor microenvironment and CCL5 for their secretion of pro-tumorigenic factors." (PMID 29216863, 2017). "Mouse survival and tumor proliferation were similar between the two groups, arguing against a major stromal source for Ccl5 in mediating the observed M-GBM survival effects." (PMID 28380429, 2017). "This relative enrichment of CCL5 expression in the mesenchymal subtype, which frequently exhibits loss of function mutations in the NF1 tumor suppressor gene, prompted us to focus on murine models characterized by Nf1 loss." (PMID 28380429, 2017). "Circulating CCL5 levels are elevated in patients with high-grade tumours compared with low-grade tumours." (PMID 27335323, 2016). "Taken together, our data suggest that radiation not only activates the STING pathway to induce Th1/Tc1 T cell activation but also activates the canonical NF-κB to increase CCL2 and CCL5 to induce Th1/Tc1 T cell tumor infiltration." (PMID 27014915, 2016). "To examine this pathway further we treated mouse and human endothelial cells, with CCL5, or tumor conditioned media, and demonstrated that migration is significantly impaired following siRNA suppression of CCR5." (PMID 27863423, 2016). "This was based on the observation that the RANTES/CCL5 chemokine is induced by MSCs following their recruitment to the tumor stroma and differentiation into CAFs." (PMID 27458162, 2016). "In a complex chemokine network in human cancers, CCL2 localizes to epithelial areas of the tumor, and CCL5 localizes with tumor-infiltrating leukocytes." (PMID 27166185, 2016). "Functional analysis of tumor microenvironment revealed a correlation between CCL5 levels and IL-6 levels." (PMID 26759169, 2016). "Here, we have developed an immunohistochemical method to detect CCL5 and IGF-1 in tumor-associated adipose tissue specimens." (PMID 27027351, 2016). "Collectively, we document for the first time that CCL5 induces tumor lymphangiogenesis by the induction of VEGF-C in human cancer cells." (PMID 27166194, 2016). "We have observed increased expression of CCL5 and cMet in tumor cells cultivated in the presence of pr.CM compared to tumor cells cultivated in CM." (PMID 26759169, 2016). "Once MSCs are recruited to the tumor microenvironment, they induce the expression of the chemokine CCL5/RANTES, which causes increased tumor neo-vascularization and aids the recruitment of other stromal cell types to encourage tumor growth." (PMID 27745603, 2016). "Global unbiased metabolomic analysis was conducted to identify any changes in levels of metabolites that occurred following CCL5 treatment of the primary MMTV-PyMT tumour cells for 3 and 6 h." (PMID 27335323, 2016). "In 20 Ewing sarcoma patients, Berghuis reported that CXCL9, CXCL10, and CCL5 that is highly expressed by tumor and stromal cells were correlated positively with accumulated CD8+ T cells." (PMID 27726306, 2016). "Here, we determine that both the CCL2:CCR2 and CCL5:CCR5 chemokine axes are uniquely modulated by RT in various tumor models." (PMID 27852031, 2016).
tumor (continued). "CCL5 produced by naive T cells and tumor cells also contributes to monocyte migration into tumor sites." (PMID 27191744, 2016). "CCL2 together with CCL5 were shown to play an important role in breast malignancy and to mediate many types of tumor-promoting cross-talks between the tumor cells and cells of the tumor microenvironment." (PMID 26759169, 2016). "To determine if RT stimulates tumor cells across different tumor models to produce the chemokines CCL2 and CCL5, we irradiated in vitro cultures of various murine and human tumor cell lines and measured CCL2 and CCL5 transcript levels by qRT-PCR." (PMID 27852031, 2016). "Ccl5 and Cxcl12 were strongly expressed in the brains of mice that developed tumours after ESC or iPSC transplantation; the expression levels of these genes were also positively correlated with the malignant grades of the tumours." (PMID 27417157, 2016). "For instance, IL-6 expression activates signalling through Janus kinase 2 (JAK2) and Stat3, EGF increases the concentration of pre-oncogenic phosphorylated Akt, whereas CXCL12 and CCL5 stimulate tumour growth through the PI3K-Akt-mTOR pathway." (PMID 27845732, 2016). "Suppression of cancer cell CCL5 lead to significantly impaired tumor growth in both syngeneic mouse models (P < 0.001)." (PMID 27863423, 2016). "Our data support an essential role of TAMs within the chemokine network, since they express 11 CCL members and three CCR receptors, of which two (CCL2 and CCL5) are also expressed by tumor cells." (PMID 27215396, 2016). "Using estrogen-supplemented oophorectomized mice bearing MMTV-PyMT mammary tumors, further studies demonstrated that inhibition of either CCL2 or CCL5 using blocking antibodies resulted in reduced macrophage infiltration and reduced tumor growth." (PMID 26884646, 2016). "For instance, high levels of CCL-5, produced by tumor cells, fibroblasts, endothelial cells, and even TAMs themselves, have been shown to positively correlate with TAM numbers in tumors." (PMID 27572316, 2016). "The Student's unpaired t test showed that the serum levels of CCL5 at baseline were significantly lower in the subgroup with tumor shrinkage (50500 ± 23800 vs. 65800 ± 23200 pg/ml, P = 0.030), while a trend was similar on day 21 after treatment start." (PMID 27166185, 2016). "In the context of a DC vaccination primed response however, VacV expressing CCL5 did significantly augment the tumor T-cell recruitment." (PMID 28536388, 2016). "Here we demonstrate that RT stimulates increased production of two chemokines, CCL2 and CCL5, at the tumor site." (PMID 27852031, 2016). "Our present study reveals miR-507/VEGF-C signaling as a novel mechanism in CCL5-mediated tumor lymphangiogenesis." (PMID 27166194, 2016). "In a spontaneous murine melanoma model CCL5 attracted MDSCs to the tumor where MDSCs promoted cancer cell dissemination by induction of EMT via TGF-β, EGF and HGF pathways." (PMID 27886105, 2016). "Increased T cell tumor infiltration is correlated with increased CCL2 and CCL5 expression in the tumor tissues." (PMID 27014915, 2016). "FAP reduction decreased transcripts for IL-10, TGF-β, CCL5 and CCL22 from CD14+ cells, of which 20-40% were F4/80+ TAMs; CCL5 transcripts were also reduced in tumor cells." (PMID 26943036, 2016). "CCL5 is one of the chemokines produced from both tumor cells and MSCs in the tumor tissues of breast cancer and prostate cancer." (PMID 25883937, 2015). "TNF-α (and IL-1β) induced the release of CCL2, CXCL8 and CCL5 by MSCs and CAFs generated by prolonged stimulation of MSCs with Tumor CM of MDA-MB-231 and MCF-7 cells." (PMID 25928089, 2015). "CCL5 has been defined in several cancers as a pro-malignant factor that correlates with poor prognosis and elevated metastasis in tumor patients." (PMID 25788271, 2015).
tumor (continued). "Accordingly, we have demonstrated that TLR3 triggering can directly induce the apoptosis of TLR3-expressing tumor cells, and the expression of chemokine CXCL10 and CCL5 which promote infiltration of T cells and NK cells into the tumor." (PMID 26287667, 2015). "High levels of CCL5/RANTES (a CCR5 ligand) and CXCL9/MIG and CXCL10/IP10 (ligands for CXCR3) in tumor tissues are associated with increased infiltration of cytotoxic effector T cells (Teff)." (PMID 26087182, 2015). "OPN expression promotes tumor growth and metastasis by activating the expression of CCL5, MMPs, and CAF in MSCs." (PMID 25885919, 2015). "Linking its expression to the CCL5/RANTES promoter or the Tie2 promoter/enhancer ensured tumor-specific expression of the suicide gene." (PMID 25879229, 2015). "Here, we establish a novel pathway for RKIP regulation of metastasis inhibition through the negative regulation of RANTES/CCL5 thereby limiting tumor macrophage infiltration and inhibition of angiogenesis." (PMID 26375811, 2015). "This surprising increase of T cell activity from spleens of older hosts due to CD2, CD3ε, CCL19, and CCL5 directly has impacted the decrease in tumor growth we observed in our earlier publication." (PMID 26497558, 2015). "These metastatic effects are partially mediated by BMDCs colonizing the primary tumor site and further secreting the pro-metastatic chemokine, CCL5." (PMID 26497998, 2015). "The CCL5 neutralizing antibodies but not control antibodies suppressed LLC invasion in both BMDC CM, indicating that CCL5 is necessary for tumor cell invasion." (PMID 26497998, 2015). "As expected, the migration of CD8+ T lymphocytes induced by tumor supernatant was partially but significantly inhibited by CCL5- and/or CXCL10-neutralizing antibodies." (PMID 26317795, 2015). "MSCs in turn have been shown to create an advantageous tumor microenvironment by the secretion of paracrine factors such as CCL5, thereby promoting tumor growth and metastasis." (PMID 25504442, 2015). "More importantly CCL5 is a key player in mediating cross-talks between tumor cells and stroma and shifting the balance to a tumor-promoting environment by recruitment of tumor associated macrophages or TAMs." (PMID 26375811, 2015). "Because of the high migratory property, MSCs promptly migrate into tumor tissues in response to the inflammatory molecules including chemokines such as CCL5 and CXCL16." (PMID 25883937, 2015). "When type 2 cells are introduced into mice, their production of TNF-α, IL-1α, or CCL5 is expected to induce the production of cytokines such as IL-6 and IL-8 in the associated fibroblast-like cells, which might in turn function as paracrine factors in tumor formation." (PMID 25673149, 2015). "In a complementary experiment, the addition of CCL5 alone was sufficient for rescuing the invasion properties of tumor cells in the presence of JDP2−/− BMDC CM to a level comparable to that found in the wild-type BMDC CM." (PMID 26497998, 2015). "Mainly, BMDCs expressing JDP2 home in large numbers to the tumor site and contribute to the secretion of the pro-metastatic CCL5 cytokine, leading to metastasis." (PMID 26497998, 2015). "Through global transcriptome analysis, immune-related functions were found to be key regulators in the spleen associated with tumor progression as a function of age with CD2, CD3ε, CCL19, and CCL5 being the key molecules involved." (PMID 26497558, 2015). "Tumor-derived CCL5 recruits MSCs to the microenvironment, and the MSCs also release CCL5 for inducing EMT in the tumor cells." (PMID 25883937, 2015). "Only CCL5 overlapped as a key factor for non-tumor bearing old mice, which means that CCL5 can be considered a natural factor that will be up-regulated as a function of age in the spleen regardless of tumor burden." (PMID 26497558, 2015).